BRAF (B-Raf proto-oncogene, serine/threonine kinase)
Diseases named in the same sentence as BRAF in open-access papers (continued):
Sharing a sentence is not in itself a finding about the gene and the disease.
melanoma (continued). "Taken together, this suggests that AXLi can potentiate BRAF-targeted therapy in various melanoma models." (PMID 35332208, 2022). "Of the 4290 patients diagnosed with irresectable melanoma between 2013 and 2017, a total of 435 patients received BRAF-MEK-inhibitors in the first line." (PMID 35703270, 2022). "An increased number of focal adhesions revealed by phospho‐paxillin staining characterized melanoma cells expressing miR‐143‐3p or miR‐145‐5p or melanoma cells upon BRAF pathway inhibition." (PMID 35156321, 2022). "Among these compounds, lj‐2‐66, containing a 2‐methyl‐7‐chloroquinoline fragment and a methylcarbazole fragment connected by a carbon atom linker, had the highest anti‐BRAF‐mutant melanoma activity." (PMID 35332658, 2022). "A phase Ib study (NCT01390818) tested MEK inhibitor pimasertib and PI3K/mTOR inhibitor voxtalisib in patients with advanced solid tumors, including TNBC and BRAFV600-mutant melanoma patients who progressed on BRAF inhibitors." (PMID 35806358, 2022). "This review discusses several combination therapies that target melanoma biomarkers, such as BRAF, MEK, RAS, c-KIT, VEGFR, c-MET and PI3K." (PMID 35954441, 2022). "Considering that in fully transformed melanoma cells, the BRAF/MEK/ERK pathway is constitutively activated for proper tumor growth, and these feedback mechanisms are likely to play a critical role in keeping MAPK activation below the viability threshold." (PMID 35580987, 2022). "Melanoma cells with BRAF deprived of exons 4–8 are selected during therapy, which leads to tumor resistance to vemurafenib." (PMID 35565444, 2022). "Follow-up experiments suggested that ZEB2 and SNAI2 act as tumour suppressors but ZEB1 and TWIST1 facilitate BRAF signalling in melanoma transformation by downregulating MITF." (PMID 35740696, 2022). "Phenotype switching in melanoma is of crucial importance when talking about resistance to BRAF inhibitors." (PMID 35956175, 2022). "NRAS mutant melanoma cells preferentially use CRAF instead of BRAF (the preferred isoform for signaling in normal melanocytes)." (PMID 36402789, 2022). "Following early preclinical evidence, several phase 2 and 3 clinical trials have investigated the efficacy of triple combination with ICIs and BRAF/MEK inhibitors in patients with advanced BRAFV600-mutant melanoma." (PMID 36428582, 2022). "This study aimed to investigate the real-world survival of patients with advanced melanoma treated with BRAF-MEK inhibitors and identify the patient, tumor and treatment characteristics of those who derive long-term benefits." (PMID 35703270, 2022). "BRAF and MEK inhibition is associated with upregulation of expression of CD47 in melanoma cells in vitro." (PMID 35492830, 2022). "Our study reveals that MARCKS is a critical mediator of enhanced metastasis in BRAF inhibitor-resistant melanoma cells and thus a reasonable, novel antimetastatic therapeutic target in patients with BRAF inhibitor-resistant melanoma." (PMID 36551563, 2022). "ZIC5 knockdown induced melanoma cell death synergistically with the BRAF inhibitor PLX40324; accordingly, we assessed if a synergistic effect would be produced by treatment with low doses of LL‐Z1640‐2 or patulin with PLX4032." (PMID 36282887, 2022). "MEK PET imaging can be used specifically for melanoma given that MEK is directly downstream of BRAF, which is constitutively activated in melanoma in more than 50% of cases." (PMID 35626272, 2022). "The role of type I IFNs in the carcinogenesis and the progression of BRAF-mutant melanoma was analyzed in a genetically manipulated mouse model where IFNAR1 was knocked out." (PMID 35269844, 2022). "Our own studies showed that BRAF inhibitors amplify the effects of MEK inhibitors in NRASmutant melanoma." (PMID 36230853, 2022). "We then focused our analysis on melanoma [Skin Cutaneous Melanoma (SKCM) TCGA cohort] and THCA, as tumors with significant percentages of BRAF mutations." (PMID 35272691, 2022).
melanoma (continued). "Annovazzi and colleagues recently investigated the prognostic value of baseline PET-derived parameter MTV and metabolic response in 57 patients affected by BRAF-mutated melanoma and monitored through 18F-FDG PET/CT during anti BRAF/MEK treatment." (PMID 35453977, 2022). "We established tri-cultures using the clinically relevant SK-MEL-28 melanoma mutant cell line, in which BRAF signaling is constitutively activated due to the substitution of valine for glutamic acid (V600E)." (PMID 35265066, 2022). "Here, we describe a novel mechanism of adaptation and tolerance to oncogenic BRAF pathway inhibition, which involves the dynamic interaction of melanoma cells with the ECM." (PMID 34957688, 2022). "French researchers evaluated exoPD-L1 levels in 46 melanoma patients during their treatment including immunotherapy and BRAF-MEK inhibitors." (PMID 36556468, 2022). "This metabolic adaptation allows BRAF inhibitor-resistant melanoma cells to survive under oxidative stress." (PMID 35053476, 2022). "In human melanoma, DGAT1 amplification was observed to co-occur with BRAF and NRAS mutation but also independently of either." (PMID 35732120, 2022). "In contrast, cobimetinib not only inhibits ERK1/2 phosphorylation but also retains the inhibitory effect of phosphorylated MEK1/2, whereas binimetinib exhibits clinical activity in both BRAF-mutated and NRAS-mutated melanoma." (PMID 36209184, 2022). "The effectiveness of MAPK pathway inhibitors (MAPKi) used to treat patients with BRAF-mutant melanoma is limited by a range of resistance mechanisms, including soluble TNF (solTNF)-mediated NF-kB signaling." (PMID 35879777, 2022). "Three combinations of BRAF inhibitor/MEK inhibitor are approved for use in the treatment of advanced BRAF mutant melanoma." (PMID 35492830, 2022). "HGF was found to provide an alternative BRAF-independent mechanism for ERK-MAPK activation to mediate resistance to BRAF-targeted therapies in melanoma." (PMID 36627901, 2022). "BRAF inhibitors have shown efficacy as a monotherapy in patients with unresectable, metastatic melanoma and as adjuvant therapy with stage III melanoma with BRAF mutations." (PMID 36232957, 2022). "Circulating tumor cells (CTCs) in melanoma patients synergistically activate adipogenesis and ion homeostasis, resulting in intrinsic and acquired resistance to BRAF inhibitors." (PMID 35847022, 2022). "Five-year OS rates were 52%, 44%, and 26% in the three groups, respectively, and among patients with BRAF-mutant advanced melanoma, 5-year OS rates were 60%, 46%, and 30%, respectively." (PMID 34818112, 2022). "As in humans, we also found that expression of zebrafish FOS orthologs is induced by oncogenic BRAF-ERK signalling in zebrafish melanomas." (PMID 36077499, 2022). "Co-treatment with a MEK inhibitor and an AXL inhibitor were synergistic in cell lines and xenograft models of TNBC, and a triplet including a BRAF inhibitor was also synergistic in melanoma models." (PMID 36358725, 2022). "Mechanisms of resistance have been studied extensively in BRAF-mutant solid tumors such as melanoma or colorectal cancer." (PMID 35205704, 2022). "In this study, we also provide evidence that SOX2 desensitizes melanoma cells to BRAF inhibition, likely by decreasing intracellular drug accumulation through transcriptional activation of the ABCG2/BCRP drug efflux transporter." (PMID 35944584, 2022).
melanoma (continued). "Although guidelines recommend automatic BRAF testing for melanoma and CRC, only about half of the hospital clinics perform the test, possibly because healthcare providers know that treatment is unavailable." (PMID 36589179, 2022). "Expression of the gain of function mutation R264C cooperated with BRAF and NRAS oncogenes to reduce mitfa expression and led to an increase in melanoma proliferation in a zebrafish model system." (PMID 35368039, 2022). "To study the function of these H3K9 and H3K27 methyltransferases in melanoma, we engineered melanocytes to express H3.3K9M and H3.3K27M in a zebrafish BRAF(V600E) melanoma model." (PMID 35223844, 2022). "This study indicates that encorafenib plus binimetinib represents a new treatment option for patients with BRAF-mutant melanoma." (PMID 36551302, 2022). "In this study, we identify the mitogen-activated protein kinase (MAPK) p38 as a novel mediator of the adaptive response of melanoma cells to BRAF-targeted therapy." (PMID 35944584, 2022). "For example, maximal suppression of BRAF-MEK signalling using combination therapy is the current standard of care for BRAF mutant melanoma patients." (PMID 35232962, 2022). "Consistent with the protumor effect of BHB, AcAc produced by upregulated HMGCL or KD promoted tumor cell growth and proliferation in BRAF V600E-expressing melanoma." (PMID 36432618, 2022). "In a less fortuitous example, targeting of BRAF mutant melanoma with the BRAF kinase inhibitor PLX4720 also drives activation of a fibrotic stromal response, which can result in therapy resistance." (PMID 35533046, 2022). "While BRAF inhibitors are the most common treatment for melanoma, their use is also limited to the approximately 40% of patients that harbor an activating BRAF mutation." (PMID 35525274, 2022). "The results indicated that lj‐2‐66 had higher selectivity for BRAF‐mutant melanoma cells than chloroquine." (PMID 35332658, 2022). "MEKi also upregulates melanoma antigen expression, even in BRAF-WT melanoma, allowing them to work with immune checkpoint inhibitors in mouse models." (PMID 35216449, 2022). "Vemurafenib was a small-molecule inhibitor of the oncogenic v-raf murine sarcoma viral oncogene homolog B (BRAF) kinase that was used for treatment of melanoma." (PMID 36246599, 2022). "In 2011, vemurafenib was the first BRAF inhibitor (BRAFi) approved by the FDA for patients with advanced melanoma." (PMID 36077308, 2022). "Combination dabrafenib (D) and trametinib (T) is an FDA approved adjuvant therapy for patients with resected stage III BRAF-mutant melanoma." (PMID 36212431, 2022). "Possibly, insulin-like growth factor 1 (IGF1) also contributes to the resistance of melanoma cells to BRAF inhibitors." (PMID 35565444, 2022). "Of note, the HP pyruvate to lactate ratio was shown to be significantly increased following single BRAF inhibition in immunodeficient mice bearing A375 human melanoma xenografts." (PMID 35327519, 2022). "Although today there are several successful melanoma therapies, such as approaches that primarily suppress the BRAF oncoprotein pathway, it is very important to investigate new therapeutic approaches and molecular targets." (PMID 36289813, 2022). "For instance, the treatment option for BRAF V600E/K-mutant melanoma is a combination of BRAF inhibitors and MEK inhibitors (BRAFi + MEKi)." (PMID 35401877, 2022). "TRIM17 augments BRAF-targeted therapy sensitivity of melanoma cells by preventing BCL2A1 from being ubiquitinated and degraded by TRIM28." (PMID 35832194, 2022). "Concomitant use of BRAF and MEK inhibitors is one of the standards of care for patients with advanced BRAF-mutant melanoma." (PMID 35893303, 2022). "Subgroup analyses were conducted by melanoma subtype and BRAF and PD-L1 status (acral melanoma only)." (PMID 36304457, 2022).
melanoma (continued). "Targeted therapies, such as BRAF inhibitors, have shown great clinical success against melanomas, but over time, cancerous cells can develop compensatory pathways, resulting in therapy resistance." (PMID 36176603, 2022). "For example, Dimitriou and colleagues reported that two patients with BRAFV600-mutant melanoma developed cytokine release syndrome (CRS) after switching to BRAF/MEK inhibitors upon progression on anti-PD-1 ± anti-LAG-3 antibodies." (PMID 35806358, 2022). "This is of particular significance for patients with BRAF-positive melanoma treated with vemurafenib, as CCL2 and myeloid cell infiltration are hallmarks of vemurafenib resistance." (PMID 35265066, 2022). "A similar approach was also explored to engineer a 3D melanoma model containing blood and lymphatic capillaries, which was responsive to the treatment with a selective inhibitor of BRAF (vemurafenib) in a dose-dependent manner." (PMID 35884596, 2022). "Selective BRAF inhibitors are very effective as monotherapy in other malignancies, such as melanoma." (PMID 36230751, 2022). "It has been shown that increased PDGFRB expression in melanoma cells makes them resistant to the BRAF inhibitor." (PMID 35565444, 2022). "Its efficiency as a combination therapy with BRAF inhibitor was recently validated in an in vivo mouse model for melanoma." (PMID 35016723, 2022). "In order to monitor the drug response to BRAF inhibitors in melanoma cells, multiple drug resistance mechanisms related to the targeted therapy of cutaneous melanoma have been discovered." (PMID 35784923, 2022). "Co-immunoprecipitation assays demonstrated that MST2 readily bound to mutant BRAFV600E in melanoma cells, whereas overexpressed wild-type BRAF only showed a weak interaction." (PMID 36038253, 2022). "Two additional BRAF V600E CDxs are approved for use in melanoma and another two for other indications, therascreen BRAF V600E RGQ PCR Kit for colorectal cancer, and OncomineTM Dx Target Test for NSCLC (not shown)." (PMID 35689144, 2022). "The activation of the MAPK pathway by BRAF and RAS gene mutations is known to increase melanoma growth, invasion, metastases, and angiogenesis." (PMID 35805104, 2022). "Metabolic reprogramming in melanoma cells is strongly linked to the constitutive activation of MAPK and PI3K signaling induced by driver mutations such as BRAF and NRAS mutants, leading to various metabolic phenotypes." (PMID 35851093, 2022). "TKI therapies were reported to be effective treatment strategies for patients with BRAF-mutant melanoma with BMs." (PMID 36354720, 2022). "Some common drugs used in targeted therapy for melanoma are vemurafenib, dabrafenib and encorafenib, which directly attack oncogenic BRAF and the MAP Kinase pathway." (PMID 35884596, 2022). "In melanoma, IDO1 expression was found to be increased in different stages of melanoma development, progression, and BRAF inhibitors resistance." (PMID 35742834, 2022). "BRAF V600E-mutant AMs are similar to low Chronic sun damage (low-CSD) melanomas, presenting fewer DNA copy number changes, whereas the histological subtype of non-BRAF V600E-mutant patients is more likely to be ALM." (PMID 35974375, 2022). "Despite promising initial response to BRAF inhibitors, melanoma progresses due to development of resistance." (PMID 36613518, 2022). "SLC7A11 has also been shown to be upregulated in BRAF inhibitor-resistant melanoma cell lines, which themselves exhibited elevated oxidative stress as compared to drug naive cells." (PMID 35326683, 2022).
melanoma (continued). "While BRAF inhibitor monotherapy in BRAFV600 melanoma leads to response rates of >50%, only ~5% of BRAFV600 CRC patients respond." (PMID 36530921, 2022). "Material and Methods: BRAF-mutant melanoma cell lines, namely M14 and A375, and their MAPKi-resistant counterparts have been subjected to: a) RNA-seq experiments and b) treatments using LNPs carrying miR-204-5p and miR-199b-5p." (PMID 35379244, 2022). "We recently showed that a novel electron transport chain (ETC) complex I inhibitor, IACS-010759 (IACS), abolished OxPhos and significantly inhibited tumor growth of high-OxPhos, BRAF inhibitor (BRAFi)–resistant human melanomas." (PMID 35193687, 2022). "In 2014, this combination was approved by the FDA for use in metastatic and unresectable BRAF V600E/K-mutated melanoma, and in 2018, this approval was extended for use in stage III melanoma." (PMID 35954441, 2022). "There is also a phase 2 BAMM2 trial examining the addition of hydroxychloroquine to dabrafenib + trametinib in patients with stage IIIC and IV BRAF-positive melanoma." (PMID 36232957, 2022). "Meanwhile, data from mouse melanoma models suggest that BRAF and MEK inhibitors can enhance the antitumor activity of immunotherapy." (PMID 36091815, 2022). "In the melanoma setting, BRAF inhibitors induce ATF4 translation through two independent signaling pathways: they trigger GCN2 kinase autophosphorylation that activates the canonical ISR, but also can sustain mTOR- and eIF4B-driven ATF4 translation." (PMID 35912100, 2022). "Although BRAF inhibitors have made great progress in the treatment of melanoma, the generation of drug resistance in tumor cells limits their efficacy." (PMID 36601121, 2022). "The combination of BRAF and MAPK ERK kinase (MEK) inhibitors is the main treatment for BRAF mutant melanoma." (PMID 36387162, 2022). "TERT promoter mutations lead to increased TERT expression and telomerase activity and are common in BRAF V600 mutant melanoma." (PMID 35903534, 2022). "A further subgroup analysis showed that low STK17B was correlated with worse OS in N and M Stage, pathologic stage, radiation therapy, gender, race, melanoma ulceration, age, melanoma Clark level, Breslow depth, tumor site, BRAF status of SKCM patients." (PMID 35171924, 2022). "Consistent with the findings in melanoma, however, reactivation of the RAS/RAF/ERK has been implicated in resistance to BRAF inhibitors in BRAFV600E pHGG." (PMID 36582791, 2022). "Tumor growth was significantly delayed in mice bearing YUMM1.7 melanoma xenografts treated with the BRAF inhibitor vemurafenib, and/or with the MEK inhibitor trametinib, in comparison with the control group." (PMID 35327519, 2022). "The authors investigated the effect vemurafenib (BRAF inhibitor) had on the RNA cargo contained within the different subsets of EVs secreted by melanoma cell lines." (PMID 35409051, 2022). "Preclinical studies using mouse models and melanoma cells lines have shown that these unfavorable immunologic features are reversed by BRAF inhibitor and MEK inhibitor." (PMID 35492830, 2022). "Activating mutations (i.e., BRAF, NRAS, etc.)are found in both benign and malignant tumors, i.e., nevi and melanoma." (PMID 36077603, 2022). "SLC35B2 expression correlates with tumor progression, and its loss decreases heparan sulfate expression, reduces receptor tyrosine kinase activity, and sensitizes resistant melanoma cells to BRAF inhibition in vitro and in vivo." (PMID 35798875, 2022). "BRAF and MEK inhibitors, target the mitogen-activated protein kinase (MAPK)/ERK signaling pathway which is constitutively active in BRAF mutant melanoma." (PMID 36119516, 2022). "Elucidating the mechanisms of resistance to BRAF inhibitors in solid tumours, especially melanoma, is an area of intensive investigation." (PMID 35158965, 2022).